NAPB (NSF attachment protein beta)
Description:
Required for vesicular transport between the endoplasmic reticulum and the Golgi apparatus.
Synonyms: SNAP-beta; SNAPB; DEE107
Tractability: Antibody: UniProt places it where antibodies can reach, with medium confidence. PROTAC: ubiquitination databases record sites on it; its protein half-life has been measured.
Gene: Protein-coding gene on chromosome 20 (23,374,519 to 23,421,519, reverse strand). Ensembl gene ENSG00000125814.
Subcellular location: Membrane
Subcellular location (Human Protein Atlas): Cytosol
Pathways (Reactome):
Vesicle-mediated transport: COPI-dependent Golgi-to-ER retrograde traffic; COPI-mediated anterograde transport; COPII-mediated vesicle transport; Intra-Golgi traffic; Retrograde transport at the Trans-Golgi-Network
Gene Ontology:
Molecular function: protein binding; soluble NSF attachment protein activity; syntaxin binding
Biological process: intracellular protein transport; regulation of synaptic vesicle priming; SNARE complex disassembly; synaptic transmission, glutamatergic
Cellular component: extracellular exosome; synaptobrevin 2-SNAP-25-syntaxin-1a complex; terminal bouton; glutamatergic synapse; membrane
Genetic constraint (gnomAD): Loss-of-function variants: 17 observed, 24.41 expected, observed/expected ratio (o/e) 0.7, 90% interval 0.48 to 1.04. The upper end of that interval is the gene's LOEUF score, 1.04, which puts it in group 4 of 6, group 1 being the genes least tolerant of losing a copy. Missense variants: 233 observed, 259.76 expected, observed/expected ratio (o/e) 0.9, 90% interval 0.81 to 1. Synonymous variants: 90 observed, 87.52 expected, observed/expected ratio (o/e) 1.03, 90% interval 0.87 to 1.23.
Homologues: Orthologues: chimpanzee NAPB (100% identical), macaque NAPB (100% identical), mouse Napb (100% identical), rat Napb (100% identical), guinea pig NAPB (99% identical), dog NAPB (99% identical), tropical clawed frog napb (95% identical), rabbit NAPB (91% identical), zebrafish napbb (88% identical), zebrafish napba (86% identical), pig NAPB (85% identical), Drosophila melanogaster alphaSnap (61% identical), and 1 more. Paralogues in human: NAPA (83% identical), NAPG (26% identical).
Diseases named in the same sentence as NAPB in open-access papers:
NAPB is named in the same sentence as 13 diseases in open-access papers, as found by Europe PMC text mining. Sharing a sentence is not in itself a finding about the gene and the disease. The quoted sentences say what the papers report.
autism (3 papers, 2021 to 2025). Persistent deficits in social interaction and communication and interaction as well as a markedly restricted repertoire of activity and interest as well as repetitive patterns of behavior. "We identified N-ethylmaleimide-sensitive factor attachment protein beta (NAPB) as a potential risk gene for autism and epilepsy." (PMID 40301471, 2025). "Alternatively, spliced isoforms of NAPB are associated with autism, and GARNL3 is linked with intellectual disability." (PMID 33423377, 2021). "Notably, Qatari monozygotic triplets with loss of function mutations in NAPB exhibit early onset epileptic encephalopathy and varying degrees of autism." (PMID 40301471, 2025). "We investigated whether a homozygous recessive genetic variant of NSF attachment protein beta (NAPB) gene inherited by monozygotic triplets contributed to their phenotype of early-onset epilepsy and autism." (PMID 38260021, 2023). "Whole exome sequencing of the parents and their monozygotic triplets, part of a Qatari cohort recruited for an autism genetics study, identified two genetic variants of potential interest: a missense mutation in VPS13B, c.8516G>A 9 (p.Arg2839Gln); and a splice site loss variant in NAPB, c.354+2T>G." (PMID 38260021, 2023).
epilepsy (3 papers, 2022 to 2025). A brain disorder characterized by episodes of abnormally increased neuronal discharge resulting in transient episodes of sensory or motor neurological dysfunction, or psychic dysfunction. "Animal models are essential for investigating the pathophysiology of neurodevelopmental disorders and epilepsy caused by NAPB mutations." (PMID 40301471, 2025). "In this study, we generated NAPB zebrafish model using CRISPR-Cas9 gene manipulation targeting the two zebrafish orthologs napba and napbb to investigate the pathology of NAPB-associated epilepsy." (PMID 40301471, 2025). "Our observations indicate that all three probands exhibit epilepsy with varying degrees of severity and frequency, underscoring the role of NAPB mutations in both ASD and epilepsy, suggesting a potential genetic overlap between these conditions." (PMID 40301471, 2025). "Previous reports have identified NAPB mutations in children with early onset epilepsy that were predicted to be protein truncating." (PMID 38260021, 2023). "In conclusion, we successfully corrected NAPB mutation and showed the restoration of genes involved in synapse function, neurodevelopmental disorders and epilepsy." (PMID 38260021, 2023). "The established NAPB zebrafish model recapitulates key features of ASD-related epilepsy, including hyperactivity and neural hyperexcitability, and represents a promising animal model for investigating seizure-like phenotypes and epilepsy-related to NAPB mutations." (PMID 40301471, 2025). "Here we are the first to provide experimental evidence for complete absence of NAPB in the neurons of probands carrying such genetic variants and provide experimental evidence for the role of NAPB protein in association with early onset epilepsy and autism spectrum disorders." (PMID 38260021, 2023). "Studies by two independent international groups have also identified two additional unique loss-of-function mutations in NAPB associated with epilepsy, further supporting the role of NAPB mutations in ASD and epilepsy." (PMID 40301471, 2025). "Here, we generated napb CR as an animal model to investigate neurological presentations, including seizure-like phenotypes and epilepsy-related to NAPB genetic variation." (PMID 40301471, 2025). "Developing animal models of NAPB genetic variants remains challenging for studying the pathophysiological mechanisms of ASD and epilepsy." (PMID 40301471, 2025). "NAPB is a new type of SNARE-associated protein, and the importance of SNARE complex in the development of epilepsy is recognized in the identification of pathogenic variants of NAPB." (PMID 36743290, 2022).
Intellectual disability (2 papers, 2021 to 2023). "There is a clinical overlap between NAPB- and VPS13B-associated neurodevelopmental features of intellectual disability, developmental delay, and autistic spectrum; however, the EOEE characterizes the NAPB phenotype." (PMID 36780047, 2023).
Cohen syndrome (1 paper, 2023). Cohen syndrome (CS) is a rare genetic developmental disorder characterized by microcephaly, characteristic facial features, hypotonia, non-progressive intellectual deficit, myopia and retinal dystrophy, neutropenia and truncal obesity. "The present pathogenic NAPB variant expands the phenotypic spectrum of Cohen syndrome and likely explains a role in the associated prominent neurodevelopmental behavioral phenotype." (PMID 36780047, 2023).
early-onset epileptic encephalopathy (1 paper, 2023). "The NAPB-related neurodevelopmental disorder is characterized mainly by early-onset epileptic encephalopathy (EOEE) and is associated with mutations in NAPB that encodes for SNAP-beta (soluble NSF attachment protein beta)." (PMID 36780047, 2023).
liver cancer (1 paper, 2022). An epithelial or non-epithelial malignant neoplasm that arises from the liver. "Moreover, TMAO upregulates POSTN, NAPB, LAYN, and HTRA3 in liver cancer, and high expression levels of these genes are closely associated with suppression of the immune microenvironment and patient survival outcomes in liver cancer." (PMID 35676936, 2022).
movement disorder (1 paper, 2022). Neurological conditions resulting in abnormal voluntary or involuntary movement, which may impact the speed, fluency, quality and ease of movement. "Usually, patients with SNAP25-DEEs show seizure's onset after 2 years of age, with generalized seizures and a frequent association to movement disorders, while NAPB-associated DEEs are characterized by a high frequency of clonic seizures and an evolution in multifocal epileptic encephalopathy." (PMID 35350397, 2022).
neurodevelopmental disorder (1 paper, 2023). A behavioral and cognitive disorder with onset during the developmental period that involves impaired or aberrant development of intellectual, motor, or social functions. "These iPSC lines will be useful to explore the molecular function of NAPB and how its dysfunction potentially contributes to the progression neurodevelopmental disorders." (PMID 38260021, 2023).
NAPB also shares sentences with these, for which no sentence is quoted: Epileptic encephalopathy (2 papers); autism spectrum disorder (1); developmental delay (1); infection (1); Onset (1).